LEP (leptin)
Diseases named in the same sentence as LEP in open-access papers (continued):
Sharing a sentence is not in itself a finding about the gene and the disease.
Obesity (continued). "Our study reveals the ubiquitous presence of leptin-reactive IgG in healthy adults of both sexes as well as in patients with obesity and T2D." (PMID 29795184, 2018). "Studies indicated that the leptin is involving in the pathophysiology of obesity and there is a positive interaction between leptin and insulin." (PMID 30360409, 2018). "Second, HFD-induced obesity promotes multiple cellular processes that attenuate leptin signaling, leading to the development of leptin resistance." (PMID 30343561, 2018). "An important characteristic of obesity is the dysregulation of adipokine levels, such as leptin and adiponectin, secreted by the adipose tissue." (PMID 30404206, 2018). "Leptin has been pointed out as a necessary factor for OA development in in vivo animal models of obesity, while studies on patients support its role in human OA, with a direct correlation between serum leptin levels and diminished cartilage thickness." (PMID 29599894, 2018). "High levels of leptin observed in obesity increases myocardial fat, reduces contractility and hypertrophy." (PMID 29417316, 2018). "In the case of progressing obesity, adipocytes produce elevated amounts of leptin, and the hypothalamic-pituitary axis becomes resistant to leptin." (PMID 29890654, 2018). "In the following sections, we will examine key aspects of leptin and adiponectin – the two most abundant and well studied adipokines – regarding their roles in brain physiology and their involvement in obesity-related cognitive dysfunction, dementia and AD." (PMID 30692905, 2018). "Omentum drives obesity progression through leptin resistance mediated by C-reactive protein, Interleucin (IL)-6 and high lipolysis activity." (PMID 29367725, 2018). "The studies reviewed here provide evidence supporting a role of leptin and adiponectin, two highly abundant and well characterized adipokines, as key mediators of obesity-related CNS dysfunctions." (PMID 30692905, 2018). "In the present study, we demonstrated that the expression of OPN and leptin was significantly increased in AR children, especially those with obesity." (PMID 30473626, 2018). "It is an anorectic agent through actions on the hypothalamus; because obese patients have a high level of serum leptin, it was thought that the main mechanism in obesity is a resistance to leptin." (PMID 30405857, 2018). "Depression is reported to have a shared biological mechanism with obesity, which js influenced by food uptake and storage of energy that are known to be regulated by leptin." (PMID 30551684, 2018). "Obesity is characterized by hyperleptinemia, and leptin administration has demonstrated to increase transcription of the myonectin mRNA in mouse myocytes." (PMID 29445355, 2018). "In obesity, leptin treatment affected PC progression and increased pancreatic cancer stem cell markers such as CD24/CD44/ESA, ALDH, CD133, and Oct-4." (PMID 30567565, 2018). "Metabolic factors of obesity, e.g. insulin, glucose and adipokines like leptin, and inflammatory factors have been related to the poor outcomes." (PMID 30034522, 2018). "Leptin resistance, characterized by elevated circulating leptin levels and decreased leptin sensitivity, is the central mechanism for the development of obesity." (PMID 29874843, 2018). "Hyperuricemia seen in obesity has been attributed to insulin resistance and higher leptin production." (PMID 29986666, 2018). "Leptin has been shown to play an important role in the pathogenesis of atherosclerosis, cardiovascular disease, inflammation, obesity and T2DM." (PMID 29785210, 2018). "In contrast to the increased level of leptin, the circulating level of adiponectin is reduced in humans with obesity and diabetes." (PMID 30423881, 2018). "A high fat/caloric diet leads to obesity, insulin resistance and increased leptin levels, all of which contribute to pancreatic adiposity." (PMID 30567565, 2018).
Obesity (continued). "Altogether these findings indicate that upon HFD, FLX is able to reduce weight gain acting on energy expenditure and to attenuate the effect of obesity on blunting leptin signaling." (PMID 29379096, 2018). "We measured affinity kinetics between plasma extracted IgG and leptin, and further evaluated their potential link with obesity and diabetes using a statistical correlation analysis." (PMID 29795184, 2018). "Leptin resistance had been confirmed to participate in the pathogenesis of obesity, the related oxidative stress and inflammation." (PMID 29615900, 2018). "What is more, T1DM people are characterized by higher leptin concentrations in comparison with healthy controls independently of obesity." (PMID 29603069, 2018). "In obesity, leptin resistance leads to increased production of leptin by adipocytes and hyperleptinemia, in an attempt of the organism to compensate for low leptin responsiveness." (PMID 30692905, 2018). "Leptin and IL-6 activate similar downstream signaling pathways and both are increased in circulation upon obesity." (PMID 30224299, 2018). "OXT synthesis in the brain hypothalamus is regulated by leptin, insulin, and dopaminergic pathways, which are particularly relevant to obesity, glucose metabolism, and addiction." (PMID 29596446, 2018). "Sel1LPOMC mice develop obesity accompanied by impaired leptin response in the POMC neurons, but the primary defect in the absence of ERAD appears to involve defective POMC processing in the ER." (PMID 29457782, 2018). "We found that FLX treatment of adult mice reduces weight gain both in normal conditions and upon obesity which correlate with higher energy expenditure, increased response to acute leptin and higher hypothalamic BDNF." (PMID 29379096, 2018). "The aim of the current study was to examine the prevalence of damaging LEP, LEPR, and MC4R mutations in Pakistani families having a recessive heritance of early-onset obesity." (PMID 30442103, 2018). "In a review entitled ‘Leptin and the control of obesity’, it was stated that ‘ATP is a major stimulus for leptin production and secretion’." (PMID 29619754, 2018). "The positive correlation of IL-10 with leptin has been documented in countering the progression of obesity and metabolic syndrome and in ameliorating inflammation." (PMID 30405010, 2018). "The stimulation of electroacupuncture significantly reduced the plasma leptin level and simultaneously elevated the level of hypothalamic serum leptin in the obesity rats." (PMID 29853949, 2018). "These inflammations increase the expression of TNF-α and NF-κB, and affect the secretion of metabolic hormones, such as insulin, adiponectin, leptin, and resistin, promoting obesity." (PMID 29707542, 2018). "Since the discovery of leptin in 1994 and the delineation of its anorectic effects, there has been a considerable interest in transforming these insights into efficacious anti-obesity pharmacotherapy." (PMID 29748097, 2018). "Given strong links between body weight and adipokines, our findings are important since the predictive value of adiponectin and leptin for PTS remained significant after adjustment for BMI as well as obesity." (PMID 29720688, 2018). "Adenosine monophosphate (AMP) kinase, a cellular energy sensor activated by cellular stresses and also by leptin and adiponectin, has fat-reducing effects in mammalian white adipose tissue and is a potential target for obesity treatment." (PMID 29619754, 2018). "We aimed to review the literature on the effects of training intervention on peripheral leptin level in obesity during aging, in order to evaluate the independent efficacy of this method." (PMID 28809927, 2017). "In the periphery, however, obesity eventually leads to inflammation of adipose tissue, and the following interplay between leptin signaling and the inflammatory cytokines secreted by macrophages seems to contribute to insulin resistance." (PMID 28303116, 2017).
Obesity (continued). "Leptin is an adipocyte-derived hormone with pro-inflammatory effects whose expression in PVAT is increased in obesity." (PMID 29234289, 2017). "In obesity, defective hypothalamic leptin signaling impairs sensing and processing of satiety signals, leading to increased caloric intake and decreased energy expenditure." (PMID 28197094, 2017). "Out of three VNTRs (D2S2221, D2S171, D2S2337) screened for association with obesity and related traits in French Caucasian families, only D2S2337 had linkage with serum leptin levels." (PMID 28615046, 2017). "LAR has also been found to be related to low grade inflammation and insulin resistance independently of obesity, with a more powerful association with CRP and HOMA-IR than leptin or adiponectin alone." (PMID 28878827, 2017). "In fact, obesity is commonly accompanied with elevated circulating leptin levels (hyperleptinemia) in proportion to the increased body fat mass." (PMID 28270795, 2017). "Though these three compounds are reported to possess anti-obesity properties, this is the first report on their protective role on leptin-induced breast cancer cells." (PMID 28930270, 2017). "This dietary regimen is responsible for the development of insulin and leptin resistance, thus leading to obesity and type II diabetes." (PMID 28804449, 2017). "We show the direct effects of adipose tissue and obesity to be blunted in female rats despite much larger changes in ADIPO:LEP ratio compared to male rats." (PMID 28676553, 2017). "In the present study, fibromyalgia patients with overweight/obesity presented lower levels of leptin than controls, a finding that differs from others in the literature." (PMID 28226002, 2017). "Since the identification of leptin (LEP) as the first obesity gene, several other Mendelian forms of non-syndromic obesity have been discovered." (PMID 29206867, 2017). "Arguably, leptin, for a while thought to be the panacea to beat obesity, received major attention in obesity research, whereas the role of insulin was less appreciated." (PMID 28303116, 2017). "As increased levels of plasma triglycerides is an indicator of leptin resistance, it would appear that males are more likely to develop obesity and leptin resistance due to high‐sugar diets compared to females." (PMID 28638713, 2017). "Our earlier studies have shown that maternal obesity elicits an exaggerated and prolonged neonatal leptin surge compared to control offspring which is thought to be a developmental cue in normal hypothalamic development." (PMID 28846730, 2017). "Similar findings by other laboratories that obesity, leptin-treatment or DCA-treatment increases permeability across intestinal epithelium support our findings." (PMID 28698546, 2017). "Obesity is a heritable disorder, and some of the many obesity susceptible genes are fat mass and obesity (FTO), leptin, and Melanocortin-4 receptor (MC4R)." (PMID 28924523, 2017). "The anorexigenic effect of leptin was lost in these mice, indicating that leptin resistance is a consequence of obesity in IFT88Δ/Δ mice." (PMID 28913352, 2017). "Contrary to leptin, the serum level of adiponectin is inversely correlated with obesity, hypertension, serum lipids and coronary artery disease." (PMID 28409493, 2017). "Obesity is characterized by low-grade inflammation, as reflected by elevated levels of leptin and hs-CRP." (PMID 28640843, 2017). "Since leptin is an adipocyte-derived hormone involved in obesity and inflammation, the specific role of leptin in the progress of ER stress-induced adipose inflammation remains to be determined." (PMID 29250056, 2017). "Among these factors, leptin and adiponectin have been proposed as key molecules linking obesity and asthmatic conditions." (PMID 28696379, 2017). "Accumulating evidence suggests that leptin and insulin are key molecules linking obesity with diseases of the lower intestine." (PMID 28170448, 2017).
Obesity (continued). "The successful identification of several obesity genes, including leptin, the leptin receptor, tubby, and agouti, suggested this strategy would be useful even when effect sizes differ by genetic context." (PMID 29194435, 2017). "Several studies have provided evidence that ER stress and the activated adaptive unfolded protein response (UPR) impair leptin signaling and are highly increased in hypothalamic neurons in the context of obesity." (PMID 28270795, 2017). "Obesity is typically characterized by excessive amounts of the hormone leptin, a cytokine-like molecule produced in white adipose tissue (WAT) that is secreted into the systemic circulation." (PMID 28321206, 2017). "Given that maternal UN gives rise to obesity and leptin resistance in later life, considerable attention has centred on the role of the adipokine leptin in the development of an aberrant offspring phenotype." (PMID 28794412, 2017). "Although leptin levels correlate with obesity and steatosis, the influence of leptin in NAFLD is still under debate." (PMID 28207798, 2017). "Increased leptin in obesity can induce adipose and placental PGE2 release contributing to inflammatory processes." (PMID 28409493, 2017). "The db/db mice on the C57BL/6 genetic background, which develop obesity secondary to leptin resistance, display noticeable elevations in blood glucose early in their lifespan." (PMID 29038790, 2017). "The DIO model, with intact leptin signaling, has been successfully used to demonstrate the effects of excessive caloric intake on obesity." (PMID 28640904, 2017). "Conversely, decreased adiponectin and increased leptin in serum contribute to the development of metabolic complications in obesity, particularly diabetes and insulin resistance." (PMID 28360931, 2017). "Leptin, which is involved in energy metabolism, significantly increases in obesity and is present in its free form." (PMID 29021781, 2017). "In the affected subjects, the disturbance of the leptin-melanocortin pathway led to extreme early-onset obesity as well as metabolic disorders, hypogonadotropic hypogonadism, and suppressed immune function." (PMID 29101506, 2017). "PC incidence and prognosis are affected by obesity, a pandemic characterized by high levels of leptin." (PMID 27999190, 2017). "Collectively, our data suggest that JNK activity promotes positive energy balance, and the therapeutic intervention inhibiting JNK activities represents a promising approach to ameliorate diet-induced obesity and leptin resistance." (PMID 28165482, 2017). "Weight gain, hyperglycemia, insulin resistance, and altered leptin and adiponectin concentrations are common effects observed in both pregnancy and obesity." (PMID 28241462, 2017). "The ob/ob mouse strain constitutes a genetic leptin-deficient monogenic model of type 2 DM that lacks functional leptin, leading to hyperphagia, obesity, hyperglycemia, hyperinsulinemia, and insulin resistance, thus demonstrating features of human type 2 DM." (PMID 29215553, 2017). "In a recent study we demonstrated that leptin and adiponectin correlate to surrogates of obesity, blood lipids and insulin resistance in sub-Saharan Africans." (PMID 28878827, 2017). "Serum leptin level was established significantly high in adolescents with obesity compared to that of control group." (PMID 28274232, 2017). "In a previous study, we have shown that the cardiac levels of leptin are associated with levels of total collagen content, collagen I and transforming growth factor (TGF)-β in diet-induced obesity in rats." (PMID 29196758, 2017). "Obesity is a chronic disorder, thus we examined the morphology of breast cancer cells after 14 days of 200 ng/ml leptin treatment in low serum conditions for changes consistent with increased invasiveness and EMT." (PMID 28542577, 2017). "Research shows that women with NWO have higher leptin levels than lean women, but lower levels than women with obesity." (PMID 28812029, 2017).
Obesity (continued). "Obesity decreased the ratio of adiponectin:leptin secreted by adipocytes, altering the adipose-dependent growth microenvironment resulting in increased breast cancer cell proliferation." (PMID 28873415, 2017). "Obesity is a chronic inflammatory disorder in which leptin, adiponectin and CRP play an important role." (PMID 27598978, 2017). "Low leptin levels are also found in those suffering from anorexia nervosa and hypothalamic amenorrhea, and conversely, high circulating leptin levels are found in obesity." (PMID 29312147, 2017). "Still, the leptin levels were well below those produced by controls with overweight/obesity matched for BMI, waist circumference (WC), and fat mass." (PMID 28226002, 2017). "Knowledge of the role of leptin within this panorama has grown to a point where some authors regard it as a programming factor for future development of obesity and its correlates, possibly via epigenetic mechanisms." (PMID 27598976, 2017). "The present data suggests an interaction between leptin and MR, which seems to be relevant in the development of cardiac fibrosis in the context of obesity in which both play a significant role." (PMID 29196758, 2017). "The timing of neonatal leptin increases influenced by fetal nutrition contributes to the development of obesity in later life." (PMID 29212463, 2017). "Consistently, increased SOCS3 expression in POMC neurons results in impaired STAT3 signaling with subsequent leptin resistance and obesity." (PMID 28270795, 2017). "As expected, there were significant reductions in leptin serum levels and hence in leptin/adiponectin ratio, which has been demonstrated to be related to obesity and T2DM." (PMID 28587203, 2017). "This signalling allows a relatively stable body weight to be maintained and in most cases of obesity a surfeit of leptin is found due to leptin resistance." (PMID 27998953, 2017). "Central leptin resistance is a hallmark of obesity, and leptin resistance in the VTA following diet-induced obesity has been noted previously." (PMID 28588553, 2017). "eQTL SNP-gene pairs for obesity and type 2 diabetes showed evidence for significant epistatic interactions within the glucose-insulin and leptin signaling pathways." (PMID 29081791, 2017). "Disruptions in any component of the leptin signaling pathway invariably leads to hyperphagia, obesity, and corollary disease in both human and rodents." (PMID 28154537, 2017). "In combination with LEP -2548GG SNP, LEP VNTR/SNP class I/G combined genotypes (I/IGG, I/IGA, and I/IIGG) were significantly associated with obesity and increased BMI, WC, leptin, and triglycerides in women." (PMID 28615046, 2017). "Adipose tissue is an active secretory organ whose secretion profile drastically changes with overweight and obesity, increasing the circulating concentrations of adipokines like leptin, or resistin." (PMID 28542472, 2017). "In mice, diet-induced obesity (DIO) results in either attenuation or elimination of cellular responses normally observed in leptin-sensitive circuits in the brain at normal weight." (PMID 28107353, 2017). "A meta-analysis of the linkage data concluded that the evidence of a gene influencing obesity in the region of the LEP locus was extremely strong." (PMID 28615046, 2017). "In this context, we demonstrated that oral administration of potential probiotic bacteria to a high-fat diet-induced obesity mice model ameliorates the alterations of leptin and cytokine levels along with partial restoration of the obesity-induced dysbiosis." (PMID 28348560, 2017). "How obesity affects an individual’s health seems to be dependent on many factors including the levels of sex steroid hormones and leptin." (PMID 28811502, 2017). "Intriguingly, leptin combats obesity through its hypothalamic actions to reduce food intake and its actions in brown adipocytes to enhance energy expenditure via promoting D2 activity and conversion of T4 to T3 in BAT64." (PMID 28128199, 2017).